AXL (AXL receptor tyrosine kinase)
Diseases named in the same sentence as AXL in open-access papers (continued):
Sharing a sentence is not in itself a finding about the gene and the disease.
cancer (445 papers, 2007 to 2026). A tumor composed of atypical neoplastic, often pleomorphic cells that invade other tissues. "Exploring the crosstalk and cooperation between AXL and other RTKs is vital for understanding the precise downstream signaling mechanisms underlying cancer cell survival." (PMID 39924521, 2025). "Specifically, these signatures indicate that high AXL expression is linked to decreased stemness in these cancers." (PMID 41048343, 2025). "AXL is expressed in many cancer types and has been associated with poor clinical prognosis and outcomes." (PMID 40696160, 2025). "In conclusion, comprehensive studies across various cancers are needed to unravel the precise molecular mechanisms underlying GAS6/AXL crosstalk with VEGFR and its regulation of angiogenic programs." (PMID 39924521, 2025). "AXL overexpression in cancer is associated with aggressive disease progression and often associated with poorer clinical outcomes in NSCLC patients." (PMID 39941857, 2025). "AXL is an inhibitor of the innate immune response, and is associated with a variety of pathological processes including cancer and autoimmune disorders." (PMID 39992996, 2025). "Cancer-associated fibroblasts (CAFs) can enhance the aggressiveness of GC cells by activating the GAS6/AXL signaling axis." (PMID 40455337, 2025). "The YAP/TAZ pathway is linked to AXL upregulation in cancer, and YAP has even been implicated as a driver of adaptive resistance to KRAS inhibitors." (PMID 39395205, 2025). "Increasing evidence has shown that the overexpression or activation of AXL is associated with metastasis, drug resistance, and poorer prognosis in many cancers." (PMID 40157901, 2025). "AXL upregulation in cancer has been linked to transcription factors SP‐1 and MZF1, as well as STAT5 activation and hypoxia." (PMID 39395205, 2025). "AXL overexpression has been linked to several key biological processes that drive cancer development and metastasis." (PMID 39924521, 2025). "Loss of AXL can lead to heightened inflammation and delayed recovery from immune-mediated damage, suggesting its potential involvement in cancer-related comorbid conditions." (PMID 39924521, 2025). "AXL, a receptor tyrosine kinase, has been implicated in the aggressiveness, metastasis, and chemoresistance of various cancers." (PMID 41366971, 2025). "To characterize cancer cell signatures in MBMs, we compared the expression of two established programs: the AXL-high program (associated with invasiveness and drug resistance) and the MITF-high program (defined by melanocyte lineage markers including MITF)." (PMID 41284647, 2025). "AXL overexpression is strongly linked to increased cell migration and invasion across various cancer types." (PMID 39924521, 2025). "AXL, a receptor tyrosine kinase related to oncogenic processes, is aberrantly expressed in various cancers and associated with treatment resistance." (PMID 41166388, 2025). "Researchers have linked elevated levels of soluble AXL to various cancers and have identified it as a cancer biomarker." (PMID 38799467, 2024). "Several studies have revealed that Gas6, which is produced by macrophages, interacts with AXL to cause cancer to develop, and AXL has been linked to worse clinical outcomes." (PMID 38391974, 2024). "The forms of hyperactivity linked to AXL are involved in the manifestation of hallmarks of some types of cancer." (PMID 38391974, 2024). "In recent years, studies have shown that high AXL expression is closely associated with treatment-resistant cancers." (PMID 37328828, 2023). "In cancer cells, these AXL-dependent signaling mechanisms are hijacked and associated with poor clinical outcomes due to loss of apoptotic potential and resistance to therapy." (PMID 37396176, 2023). "Based on a large body of evidence, cancer progression is frequently associated with acquired resistance to the inhibitors of EGF receptor (EGFR) mediated by the enhanced AXL expression as a bypass mechanism." (PMID 37469409, 2023).
cancer (continued). "Intriguingly, AXL is the top ranked DEG associated with T cell dysfunction in multiple cancer types." (PMID 36588164, 2023). "AXL has been associated with poor prognosis in many cancer types, including RCC and resistance to therapies." (PMID 37370768, 2023). "AXL is a tyrosine kinase receptor expressed in various cancer types and associated with poor prognosis and resistance to treatment." (PMID 36813833, 2023). "Although these studies clearly demonstrate that AXL positively regulates autophagy, the underlying molecular mechanism remains poorly understood in cancer cells." (PMID 35936716, 2022). "AXL signaling has also been associated with immunosuppressive macrophages in a cancer context where conditioned media from AXL expressing cancer cells cause macrophages to polarize in vitro." (PMID 35158733, 2022). "In an unbiased analysis of 643 human cancer cell lines, AXL was strongly associated with a drug-resistant mesenchymal phenotype, and inhibition of AXL displayed a specifically synergistic effect together with antimitotic drugs such as docetaxel." (PMID 35572601, 2022). "AXL has been implicated in metastasis of numerous cancers, including breast, ovarian, colon, thyroid, lung, liver and others." (PMID 36551940, 2022). "Recently, immunohistochemistry (IHC) labeling of AXL in a series of more than 300 clear cell RCC (ccRCC) tissues revealed that high AXL expression is associated with increased expression of PD-L1 on carcinoma cells." (PMID 35572601, 2022). "AXL is a receptor tyrosine kinase expressed in many cancer types and has been associated with therapy resistance and poor clinical prognosis and outcomes." (PMID 33828969, 2021). "The exclusive role of AXL in cancer progression is likely associated with AXL normal function in clearance of apoptotic cells and immunosuppression." (PMID 34638349, 2021). "Linking the AXL-specific IgG1 and MMAE enables enapotamab vedotin to target the AXL-positive cancer cells and cause inhibition via MMAE." (PMID 34203870, 2021). "AXL up-regulation in several human cancers including TNBC is frequently associated with resistance to different chemotherapeutic agents and targeted therapies, including MEK, PI3K/AKT, BET, and EGFR." (PMID 33785524, 2021). "Firstly, the AXL gene is rarely amplified or mutated in human cancer, which is in stark contrast to some other RTKs." (PMID 34638349, 2021). "The present paper reports the use of LAMP in core-shell beads to detect AXL overexpression as a potential diagnostic tool for cancer detection." (PMID 34442532, 2021). "Here, we discuss AXL function in normal homeostasis and review the current literature on the underlying mechanisms to explain the distinctive role of this receptor in cancer biology." (PMID 34638349, 2021). "Among RTK family, the TAM (Tyro-3, AXL, Mer) kinases have been implicated in the development of a serial of cancers." (PMID 34831142, 2021). "In this review, we outline molecular mechanisms underlying AXL function in normal tissues, and discuss how these mechanisms are adopted by cancers to become metastatic and drug-resistant." (PMID 34638349, 2021). "AXL expression is associated with various processes in cancer, including proliferation, survival, metastasis and resistance to cancer therapy." (PMID 34006939, 2021). "Here, we provide evidence that AXL knock-out alone is sufficient to block the survival of cancer cells by a mechanism associating G2 arrest with polyploidization." (PMID 34948046, 2021). "Since then, AXL is found to be overexpressed in many types of cancer and is associated with therapy resistance, adverse prognosis, and worse outcome." (PMID 34497683, 2021). "Among the essential cytoskeleton regulators, AXL overexpression, a receptor, tyrosine, has been observed in different cancers and associated with an aggressive phenotype, invasiveness and progression." (PMID 34831142, 2021).
cancer (continued). "AXL has been broadly implicated in the epithelial-mesenchymal plasticity of cancer cells, a key factor in drug resistance and metastasis." (PMID 34638349, 2021). "Recently, AXL has been implicated in therapy resistance to multiple targeted therapies and cancer types, including MPNST." (PMID 32245042, 2020). "Known resistance factors to EGFR-targeted therapies in other cancer types include mutations and overexpression of the receptor tyrosine kinases AXL or MET." (PMID 32119655, 2020). "This study was conducted to investigate the mechanism underlying the anti-cancer effects of cabozantinib through regulation of AXL and MET signaling." (PMID 32055714, 2020). "It has been shown that GAS6, released by stromal cells, activates AXL and its molecular targets in cancer cells and causes alterations in E-cadherin expression." (PMID 33182542, 2020). "AXL therefore plays a role in cancer progression, and AXL has been implicated in a wide variety of malignancies from solid tumors to hematopoietic cancers where it is often associated with poor prognosis." (PMID 32148495, 2020). "Receptor tyrosine kinase AXL is a one-pass transmembrane protein upregulated in cancers and associated with lower survival and therapy resistance." (PMID 31917795, 2020). "Another Japanese group also demonstrated that AXL played a key role in EGFR-mutated cancer cell survival against osimertinib, which they referred to as ‘intrinsic resistance’20." (PMID 31900393, 2020). "In particular, a high expression of AXL in malignant tumors has been associated with a poor prognosis." (PMID 33374832, 2020). "Overexpression or activation of AXL has been clinically linked to high invasiveness and metastasis in various cancers." (PMID 32055714, 2020). "The up-regulation of AXL causes the phosphorylation of Smad3, which is regulated by TGFβ signaling and is well correlated with an increase in the metastasis of cancer." (PMID 32324796, 2020). "Since deregulated AXL expression is associated with cancer and other pathological conditions, a better understanding of AXL regulation is critical for AXL-targeted treatment approaches." (PMID 31171001, 2019). "Hypomethylation of the AXL gene has been associated with high expression in different cancer entities." (PMID 31171001, 2019). "To explore the possible clinical associations between PTBP1 and AXL, we made use of the Oncomine cancer profiling database and conducting lung tissue microarray analysis." (PMID 31729427, 2019). "NPS-1034 is a newly developed dual AXL/MET inhibitor that exerts efficacy against cancer cells harbouring activated or mutated MET or AXL." (PMID 31684958, 2019). "We show that BRAF and AXL oncogene overactivation in cancers is likely to be among the driving forces for the loss of RIPK3 during tumorigenesis and the consequent escape from necroptosis, as well as other RIPK3-driven processes." (PMID 30157175, 2018). "Nonetheless, miR-199a1 expression was marginally associated with lower AXL mRNA expression, which is consistent with the previously reported role of miR-199a1 to negatively regulate AXL expression in cancer cell lines." (PMID 30029617, 2018). "BRAF gain-of-function mutations and AXL overexpression, which are both observed in various cancers at high frequencies, are important therapeutic targets for the treatment of cancers." (PMID 30157175, 2018). "We discover BRAF and AXL as the first two oncogenes that can drive the loss of RIPK3 expression in cancer cells." (PMID 30157175, 2018). "AXL also is implicated as having a functional role in cells that possess cancer stem cell (CSC) activity." (PMID 29719832, 2018). "Overexpression of AXL is associated with several aspects of cancer such as proliferation, epithelial–mesenchymal transition (EMT), invasion, and resistance to drug treatment." (PMID 30353671, 2018). "Recently, overexpression of AXL has been demonstrated to cause drug resistance in various cancer cells." (PMID 28034848, 2017).
cancer (continued). "Recently, increased expression or abnormal activation of AXL has particularly been implicated in resistance to cancer chemotherapy and targeted therapy." (PMID 28455956, 2017). "AXL is involved in several cellular functions including growth, migration, aggregation and anti-inflammation, which are also associated with cancers." (PMID 27100677, 2016). "Activating mutations within the AXL kinase domain are rarely found in cancer (The Cancer Genome Atlas, TCGA)." (PMID 27834845, 2016). "Higher expression levels of AXL are implicated in proliferation, migration, and resistance to therapy of many cancers." (PMID 26798410, 2016). "Although the mechanisms underlying the link between cancer cells and TAMs are complex and difficult to dissect in vitro, we observed the reciprocal nature of this interaction sustained by AXL." (PMID 28721387, 2016). "Of the three genome-wide suggestive probes, cg27094856 was located in the fourth intron of the AXL gene, which is implicated in many cancers and is a therapeutic target for antibody-based therapies." (PMID 26798410, 2016). "Higher expression levels of AXL are found in many cancers tissues and implicated in proliferation, migration, and therapy resistance." (PMID 26798410, 2016). "The induction of AXL or MET is associated with increased cellular mobility in cancers.We therefore investigated changes in cellular mobility in both the parental and gefitinib/erlotinib-resistant cells." (PMID 25780909, 2015). "Distinct from many other receptor tyrosine kinases, AXL mutations are rarely found in cancer, suggesting elevated AXL expression is responsible for its oncogenic effect." (PMID 26356563, 2015). "Although, it seems well established that AXL is involved in resistance to chemotherapy in cancer cells, the mechanisms underlying AXL overexpression in this context remain unexplored." (PMID 22141136, 2011). "Furthermore, AXL signaling in Schwann cells and neurons is implicated in neuropathic pain, which is a common and debilitating comorbidity in advanced cancer patients." (PMID 41383633, 2025). "In conclusion, while numerous cancer studies have demonstrated the potential of AXL as a biomarker and therapeutic target, further research is warranted to ascertain the clinical utility of AXL-based diagnostic and treatment tools." (PMID 39924521, 2025). "Furthermore, AXL upregulation in cancer resistance has been linked to the AP‐1 transcription family, which can be activated downstream of ERK signaling." (PMID 39395205, 2025). "Notably, the overexpression of AXL in these three cancer types is a risk factor across three to four metrics of patient survival." (PMID 41048343, 2025). "Further exploration of the mechanisms underlying receptor switching from PDGFR to AXL in different cancers could provide valuable insights into the signaling networks and help overcome acquired resistance." (PMID 39924521, 2025). "The dysregulation of phosphorylation pathways, including those involving AXL, is linked to cancer." (PMID 39597836, 2024). "In addition, AXL is associated with higher-grade cancers, treatment resistance, and overall poor prognosis." (PMID 37370772, 2023). "Various cancer models have linked AXL with immune suppression." (PMID 37370768, 2023). "AXL is a receptor tyrosine kinase commonly associated with a variety of human cancers." (PMID 37396176, 2023). "There might be a protective role of cholesterol in shielding cancer cells against DNA damage induced by AXL inhibition or SMA68 deficiency." (PMID 37349576, 2023). "However, the precise mechanisms underlying AXL-mediated drug resistance in cancer cells remain largely unclear." (PMID 37328828, 2023). "TAMs have also been implicated in cancer, with AXL playing a prominent role in cancer progression." (PMID 35622156, 2022). "In contrast to many other RTKs associated with cancer, genetic aberrations of AXL are uncommon." (PMID 35572601, 2022).
cancer (continued). "AXL has been associated with a range of cancers with poor clinical outcomes." (PMID 35054460, 2022). "The receptor tyrosine kinase AXL—initially identified to be overexpressed in human myeloid leukemia cells—has, over the years, emerged as a promising diagnostic and therapeutic target for a range of cancers." (PMID 34442532, 2021). "However, the underlying mechanism of AXL induction in mesenchymal cancer cells is poorly understood." (PMID 33207077, 2021). "Interestingly, while AXL is expressed in mouse embryos, it is implicated in cancer EMT and EMT drives critical stages of embryonic development." (PMID 34638349, 2021). "The tyrosine kinase AXL has been implicated in cancer metastasis." (PMID 33917370, 2021). "Interestingly, in pan-cancer cohorts, high AXL is associated with poor RFS in patient samples with enriched mesenchymal stem cells." (PMID 33850249, 2021). "Additionally, AXL has been implicated in resistance to a variety of other targeted therapies in other cancer types, including vemurafenib, sunitinib, alpelisib, crizotinib, and imatinib." (PMID 32148495, 2020). "Additionally, AXL has been implicated in metastasis, invasion, and migration in diverse human cancers." (PMID 33374832, 2020). "It has been hypothesized that AXL could serve as a therapeutic target to reactivate the dormant cell population, making them more susceptible to chemotherapy and eradicate residual cancer cells in MM." (PMID 31694201, 2019). "Because 90% of cancer-related deaths are caused by metastasis and since AXL plays a major role in this process, we investigated whether phenothiazine treatment also impacted the metastatic progression of injected TNBC cells." (PMID 31007848, 2019). "Interestingly, nearly 18% of these genes were found to associated with a SE and included AXL, a known regulator of cancer associated EMT." (PMID 31306413, 2019). "AXL is associated with cancer invasion/progression, investigation of its gene regulation is of great importance, especially for its down regulation and/or inhibition in terms of clinical implications of counteracting cancer metastasis and reversing drug resistance." (PMID 31729427, 2019). "Recent studies have implicated AXL as an important factor driving the cancer stem cell phenotype." (PMID 27834845, 2016). "In this respect, several studies suggest that overexpression of AXL may be implicated in resistance to both targeted therapies and conventional chemotherapy in different cancer models." (PMID 25966280, 2015). "We investigated the mechanism(s) responsible for this ERK reactivation and hypothesized that targeting tyrosine‐protein kinase receptor UFO (AXL), another receptor tyrosine kinase that has been implicated in cancer resistance, may overcome the adaptive ERK reactivation." (PMID 39395205, 2025). "AXL expression is up-regulated in numerous human malignancies, such as leukaemia, breast cancer, prostate cancer, kidney cancer, melanoma, glioblastoma and non-small lung cancer, and it is associated with cancer progression, therapy resistance and poor prognosis." (PMID 41004176, 2025). "Recurrent or aberrant activation of AXL has been observed in several pathologies that exploit to their advantage the activation of pathways linked to AXL, in particular, the diseases that most exploit this ‘jammed’ mechanism are cancer, chronic immune disorders and cardiovascular disease." (PMID 38391974, 2024). "Interestingly, the signal from AXL may induce low-fidelity DNA polymerases and Myc, thereby evolving tolerance towards endogenous mutators and antibiotics, as well as drugs in cancers." (PMID 38892166, 2024). "Interestingly, AXL deficiency resulted in a loss of regulatory DCs in cancer models." (PMID 35300973, 2022). "In addition, cancer-associated fibroblasts (CAFs) expressed AXL, showing that CAF abundance might be linked to preferential expression of the AXL over the MITF program." (PMID 35054460, 2022).